LINC01539 (long independently transcribed non-coding RNA 1539)
Synonyms: LINC03069
Gene: Long non-coding RNA gene on chromosome 18 (56,003,612 to 56,191,262, reverse strand). Ensembl gene ENSG00000267712.
Diseases named in the same sentence as LINC01539 in open-access papers:
LINC01539 is named in the same sentence as 4 diseases in open-access papers, as found by Europe PMC text mining. Sharing a sentence is not in itself a finding about the gene and the disease. The quoted sentences say what the papers report.
cancer (1 paper, 2024). A tumor composed of atypical neoplastic, often pleomorphic cells that invade other tissues. "The more cancer-specific lincRNAs are LINC00470, LINC00668, LINC00907, LINC01254, LINC01415, LINC01478, and LINC01539." (PMID 38540157, 2024).
LINC01539 also shares sentences with these, for which no sentence is quoted: acute myeloid leukemia (1 paper); testicular germ cell tumor (1); thyroid cancer (1).